Y_RNA (Y RNA )
Gene: Miscellaneous RNA gene on chromosome 2 (147,472,133 to 147,472,243, reverse strand). Ensembl gene ENSG00000207161.
Homologues: Orthologues: chimpanzee Y_RNA (98% identical), macaque Y_RNA (92% identical). Paralogues in human: Y_RNA (83% identical), RNY1 (82% identical), Y_RNA (82% identical), Y_RNA (81% identical), RNY1P8 (80% identical), Y_RNA (80% identical), RNY1P5 (79% identical), Y_RNA (79% identical), RNY1P11 (78% identical), RNY1P16 (78% identical), Y_RNA (78% identical), RNY1P7 (77% identical), and 93 more.